RN7SL147P (RNA, 7SL, cytoplasmic 147, pseudogene)
Gene: Miscellaneous RNA gene on chromosome 3 (11,952,788 to 11,953,085, reverse strand). Ensembl gene ENSG00000263988.
Homologues: Orthologues: chimpanzee Metazoa_SRP (99% identical), macaque Metazoa_SRP (93% identical). Paralogues in human: RN7SL2 (88% identical), RN7SL1 (87% identical), RN7SL3 (86% identical), RN7SL126P (84% identical), RN7SL145P (83% identical), RN7SL326P (83% identical), RN7SL44P (83% identical), RN7SL650P (83% identical), RN7SL448P (82% identical), RN7SL18P (82% identical), RN7SL444P (82% identical), RN7SL664P (82% identical), and 703 more.